IL6 (interleukin 6)
Diseases named in the same sentence as IL6 in open-access papers (continued):
Sharing a sentence is not in itself a finding about the gene and the disease.
lung carcinoma (continued). "Since IL-6 and MCP-1 are pathologic markers of glomerulopathy, their distributions were examined in the kidneys of the lung cancer mice." (PMID 33260558, 2020). "Knocking down FAS activates NFkB signaling and subsequent IL6 secretion, resulting in phosphorylation of signal transducer and activator of transcription 3 (STAT3) to promote lung cancer cell growth." (PMID 32963220, 2020). "In HT-29 colorectal cancer cells and H1299 lung cancer cells, we observed that choloroquine and hydroxychloroquine increase expression of ACE2, TMPRSS2 and IL-6." (PMID 33245731, 2020). "The PI3Kγ inhibitor AS-605240, another top candidate, was found to suppress lung carcinoma inflammation and the secretion of pro-inflammatory cytokines (e.g. IL-17, IFN-γ, IL-22, GM-CSF, IL-6, IL-4, and IL-13)." (PMID 33381110, 2020). "For example, activation of TLR2 or TLR4 signals on TAMs increases the lung cancer metastasis via TNF-α and IL-6 production." (PMID 32788720, 2020). "Significantly elevated expression of IL1-β, IL-6, IL-8, IL-10, IL-17, TNF-α, TGF-β, IFN-γ, and C-X-C motif chemokine ligand 1 (CXCL1) has been seen in colorectal cancer and other solid cancers like lung cancer." (PMID 32425932, 2020). "Previous research also confirms that RAs produce IL-6, tumor necrosis factor-α (TNF-α), and IL-1β, all of which promote lung cancer brain metastasis." (PMID 33262947, 2020). "To further demonstrate the relationship between p65, IL6, and STAT3 signaling, we overexpressed p65 in lung cancer cells." (PMID 32963220, 2020). "We found that the effect of IL‐6 promoting EMT of lung cancer cells was weakened in TIM‐4 shRNA group, and TIM‐4 knockdown significantly reversed IL‐6‐induced migratory ability and invasive activity in vitro." (PMID 32020709, 2020). "Expression of CCL2, CCR2 or in combination with IL6 and IL10 correlates with a worse prognosis in lung cancer patients." (PMID 32219066, 2020). "To further demonstrate underlying molecular mechanisms of FAS knockdown-mediated enhancement of IL6 expression, we investigated p65 protein nuclear translocation in FAS knockdown lung cancer cells." (PMID 32963220, 2020). "The increased serum concentration of several cytokines, including VEGF, IL-6, TGF-β, and TNF-α, have been proposed as lung cancer biomarkers." (PMID 33125430, 2020). "It has been previously reported that TLR4-induced autophagy activation promoted migration and invasion of lung cancer by induction of chemokines and immunosuppressive factors including CCL2, CCL20, IL-6, VEGFA, and MMP2." (PMID 32384667, 2020). "Therefore, targeting IL-6 in lung cancer patients may improve response to immunotherapy." (PMID 33375062, 2020). "Baicalin can reduce lung cancer metastasis by reducing HIF-1α level and can reduce the expression levels of RAGE, IL-6, and TGF-β1 to improve pulmonary hypertension." (PMID 33149752, 2020). "Therefore, blockade of IL-6 signaling may act as an effective treatment for lung cancer." (PMID 31491033, 2019). "Here, we investigated the role of miR‐206 in regulating IL‐6/STAT3 pathway and gefitinib resistance in lung cancer." (PMID 31507089, 2019). "Overall, our results elucidated a crucial role of LDOC1 in lung cancer and revealed how LDOC1 acts as a bridge between tobacco exposure and the IL-6/JAK2/STAT3 loop in this human malignancy." (PMID 30634502, 2019). "The pro-inflammatory cytokine interleukin-6 (IL-6) has been shown as an important EMT inducer in breast and lung cancers." (PMID 30744595, 2019). "In parallel, we adapted two EGFR‐mutant and TKI‐sensitive lung cancer cell lines, PC‐9 and HCC827, to IL‐6 and cultured for 72 hours to simulate the in vivo microenvironment." (PMID 31507089, 2019). "Taken together, our findings reveal a direct role of miR‐206 in regulating IL‐6/STAT3 pathway and contrarily activated IL‐6/STAT3 signalling mediates the miR‐206 maturation process in gefitinib‐resistant EGFR‐mutant lung cancer cells." (PMID 31507089, 2019).
lung carcinoma (continued). "However, whether E2 stimulation can mediate IL6 expression in lung cancer was unclear." (PMID 29970138, 2018). "In lung cancer cells, AhR-RelA dimers bind to a DRE-independent NF-κB response element in the IL-6 promoter, resulting in increased IL-6 expression." (PMID 30563036, 2018). "Previous studies have shown IL-1, IL-6, and TNF-α increase in lung cancer patients and these cytokines progressively decrease as the clinical stage of cancer progresses." (PMID 30365491, 2018). "Therefore, to investigate the relationship between E2, ERβ and IL6 in lung cancer and test the hypothesis that E2 up-regulates IL6 through ERβ to promote lung cancer progression, in the present study, we demonstrate that both IL6 and ERβ expression regulate clinicopathological factors in NSCLC." (PMID 29970138, 2018). "In the human lung cancer cells, from which the CM was derived for the ex vivo culture, TNF, IL6 and IFNB1 were upregulated upon Snail OE, while IFNG was undetectable." (PMID 30190790, 2018). "Previous clinical studies which have assessed changes in plasma cytokine concentration during radiotherapy for lung cancer have demonstrated increased circulating TGF-β143, IL-6 and IL-1044, and MCP-3, δMIP-1a, and IP-1045." (PMID 30190567, 2018). "Using the MEK inhibitor U0126 and the PI3K inhibitor LY294002 to treat lung cancer cells, we found that the MAPK/ERK and PI3K/AKT pathways are involved in the regulation of IL6 expression." (PMID 29970138, 2018). "However, whether E2 mediates IL6 expression in lung cancer is unknown." (PMID 29970138, 2018). "In lung cancer models, tarin decreased metastasis by leading to an increase in the levels of TNF-alpha, IL-6, and IL-12 cytokines." (PMID 30403726, 2018). "To further explore which cells contribute to TNF-α and IL-6 production, we also detected TNF-α and IL-6 expression in AFG1-induced lung cancer cells as well as in tumor-adjacent tissues by immunohistochemical staining." (PMID 28801561, 2017). "In the current study, we demonstrate, for the first time, that ING5 knockdown promotes invasion of lung cancer cells by inducing EMT via EGFR/PI3K/Akt and IL-6/STAT3 signaling pathways." (PMID 28903339, 2017). "Abnormalities in the IL-6/JAK/STAT3 pathway are also due to expression of a variety of oncogenes, such as Myc and VEGF, reportedly increased in lung cancer and other cancer types." (PMID 28830450, 2017). "Our data supports that polyI:C (its analogue, Hiltonol) is a promising adjuvant in combination with anti-IL6 antibody and/or JAK2/STAT3 inhibitors, for lung cancer immunotherapy." (PMID 28427199, 2017). "In selected lung cancer cell lines, persistently activated or tyrosine-phosphorylated STAT3 is partially due to IL-6 induction, and IL-6/p-STAT3 pathway activation is confirmed to be critical for lung cancer progression." (PMID 27992365, 2017). "Our study, both in vitro and in vivo, demonstrated that CAFs activated IL-6/STAT3 signaling pathway, leading to the enhanced metastasis potential of lung cancer." (PMID 29100297, 2017). "We next investigated the effect of IL-6 on EMT status and metastasis-related genes in lung cancer cells." (PMID 29100297, 2017). "In order to correlate our findings with lung cancer prognosis in clinical settings, we analyzed the data from 1405 lung cancer patients and the gene expression of miR-218 host genes (SLIT2/SLIT3), IL-6, IL-6R, JAK3 and STAT3 in their tumor tissues." (PMID 28830450, 2017). "Consistent with the reported effect of IL-6 on MUC1 overexpression in breast and lung cancer cells, exposure of AsPC-1 cells to IL-6 led to parallel increases in STAT3 phosphorylation and the expression of MUC1-C, and, to a lesser extent, ILK." (PMID 28692035, 2017). "6-OAP formed hydrogen bonds with Ser611/Ser613/Arg609 at the SH2 domain of STAT3 and inhibited the constitutive and interleukin-6-induced phosphorylated STAT3 (pSTAT3), leading to inhibitory effects on lung cancer cells and suppression of Skp2 transcription." (PMID 27835873, 2017).
lung carcinoma (continued). "Our study demontrated that the TGF-β and IL-6/JAK2/STAT3 signaling pathways form a positive feedback signaling loop that mediated the interactions between MFs and lung cancer cells." (PMID 28819126, 2017). "That study detected the contents of such plasma cytokines as IL-1, IL-6, IL-10, tumor necrosis factor α (TNF-α), and TGF-β1 in 34 lung cancer patients at different time points and found the incidence of SRP as 23.5%." (PMID 29147071, 2017). "We previously demonstrated that lung cancer cells and fibroblast cells interact through TGF-β and IL-6 pathways; IL-6 enhances EMT and tumor progression by stimulating TGF-β signaling." (PMID 28878389, 2017). "Our results will provide a better understanding of the communication among IL-17, IL-6, IL-8, and VEGF as well as new insights into the targeting of inflammation and angiogenesis for the treatment of lung cancer." (PMID 27819281, 2016). "We also found that the expression of IL-6, CXCL16, or IGFBP-4 significantly predicted the poor overall survival in patients with lung cancer." (PMID 27095254, 2016). "For instance, the SAA1 lung cancer biomarker, neuro-inflammation factor MMP1, the chemokine ligands (C-C motifs) CCL2, CCL5, and CCL20, and cytokines such as IL6, IL8, IL16, were all significantly modulated." (PMID 26950733, 2016). "To clarify the hypothesis that overproduction of IL-6 elevates hepcidin levels and contributes to the development of cancer-related anemia, we evaluated anti-IL-6 receptor antibody treatment of cancer-related anemia in an IL-6–producing human lung cancer xenograft model." (PMID 27068103, 2016). "As ATM-NF-κB pathway is involved in IL-6-increased cell migration, we next explored the role of ATM-ERK/p38-NF-κB activation in TNF-α promoting lung cancer cell migration." (PMID 27556690, 2016). "Some of these cytokines (IL-6, IL-8, IL-10, IL-22, VEGF, TGF-β, and TNF-α) have also been studied to determine their role in lung cancer and are described in comparison to other cytokines next." (PMID 27445423, 2016). "As MMP-13 is closely involved in IL-6 or TNF-α increasing tumor metastasis, we therefore focused on MMP-13 in TNF-α increasing lung cancer cell migration." (PMID 27556690, 2016). "Metformin has been demonstrated to sensitize EGFR tyrosine kinase inhibitor (TKI)-resistant lung cancer cells by reversing the EMT and decreasing IL-6 signaling activation." (PMID 27519177, 2016). "Together, we demonstrated dual roles of IL-6 in regulating growth of CD133– and CD133+ subpopulations of lung cancer cells and significant regulation of IL-6 on EMT/metastasis increase in CD133+ cells, not in CD133– cells." (PMID 26675547, 2016). "We examined expression of IL-1A, IL-1B, IL-6 and IL-8 in two pairs of gefitinib-sensitive (PC9, and HCC827) and gefitinib-resistant (PC9/gef, and HCC827/gef) lung cancer cell lines to identify the specific cytokine involved in gefitinib resistance by RT-qPCR." (PMID 25871388, 2015). "Here, we investigated the role of ATM phosphorylation in IL-6 increasing MMP-3/MMP-13 expression, but the exact mechanism by which MMP-3/MMP-13 promoting lung cancer metastasis is still to be clarified." (PMID 26528698, 2015). "The present study demonstrated that high IL-6 level increases both expressions and activities of MMP-3 and MMP-13, hence augments cell migration abilities of lung cancer." (PMID 26528698, 2015). "The inflammatory cytokines, TNF-α, IL-1 and IL-6 are elevated in COPD, CVD, and lung cancer and are potential therapeutic targets particularly in the context of acute exacerbations." (PMID 26220864, 2015). "In the present study, we found that the high IL-6 level reveals both the increased expression of MMP-3/MMP-13 and the enhanced migration abilities of lung cancer cells." (PMID 26528698, 2015). "In different studies, IL-6 production has been reported in several tumors in humans such as esophageal SCC, multiple myeloma, renal cell carcinoma, glioblastoma, and lung carcinomas." (PMID 26082901, 2015).
lung carcinoma (continued). "Then, the inhibition of ATM phosphorylation abolishes IL-6 increased expression of MMP-3/MMP-13, hence abrogates IL-6 correlated lung cancer metastasis both in vitro and in vivo." (PMID 26528698, 2015). "To demonstrate the critical role of the TNF-α/NF-κB/cyclinD1 and IL-6/STAT3/cyclinD1 pathways in the malignant transformation of 16HBE cells, we first detected the expression levels of TNF-α, IL-6, NF-κB, STAT3, and cyclinD1 in lung cancer tissues." (PMID 25823926, 2015). "Activation of STAT3 by IL6, or overexpression of total or phosphorylated STAT3 significantly suppressed crizotinib-induced autophagy in lung cancer cells." (PMID 26384345, 2015). "For this, we treated A549 lung cancer cells with TNFα, IL1β, E. coli lipopolysaccharide (LPS), as well as IFNγ, and assessed secretion of the cytokines CXCL10, IL6 and IL8." (PMID 26030458, 2015). "Therefore, as a preliminary step, we have determined here whether serum IL-6 is a reliable surrogate marker for use in patients with lung cancer and cachexia, and verified the efficacy of MR16-1 in our previously established experimental model of that condition." (PMID 25010770, 2014). "One previous study found that TAS was positively correlated with proinflammatory cytokines IL-1α, IL-6, and TNF-α in bronchoalveolar lavage fluid in lung cancer patients." (PMID 25254081, 2014). "Significantly elevated IL-6 levels have been detected in BAL cell cultures and blood from patients with lung cancer compared to those with benign disease." (PMID 26316944, 2014). "A recent study investigated IL-6 levels in BAL fluid and serum from patients with lung cancer before and during radiotherapy (RT)." (PMID 26316944, 2014). "It has been reported by other groups that IL-6, VEGFA and PDGFDB were significantly up-regulated in macrophages isolated from tissues of human lung cancer and glioblastoma." (PMID 24194900, 2013). "In our study, the regulation of TF by IL-6/JAK2/Stat3 signaling, which participates in metastasis, was also confirmed in lung cancer cells." (PMID 24086497, 2013). "Recent studies also mention that A. sinensis has the ability to suppress the expression of TGF-β1 in lung cancer study and the expressions of TNF-α and IL-6 in chronic inflammatory diseases." (PMID 24069047, 2013). "Weight loss, lean body mass decrease, and hypermetabolism are highly correlated to both the elevated levels of proinflammatory cytokines, such as IL-1β, IL-6 and TNF-α and the decreased level of albumin in lung cancer patients." (PMID 23349693, 2013). "We have previously revealed increased levels of IL-6 and subsequent activation of the STAT3 pathway in our K-ras induced mouse model of lung cancer in absence and presence of COPD-like airway inflammation." (PMID 24321240, 2013). "For example, aberrant EGFR signaling in glioblastoma, lung cancer and MCF10A cells led to enhanced IL-6 production and signaling." (PMID 20929542, 2010). "The mean IL-6 concentrations were significantly higher in the lung cancer patients than in the normal controls, and the patients with metastatic tumor had higher IL-6 levels than those patients with undisseminated disease, suggesting that neoplastic cells may produce IL-6." (PMID 19943923, 2009). "However, whether interleukin-6 is produced directly by lung cancer cells remains unclear." (PMID 12966420, 2003). "In a lung cancer model, tumor resection led to increased levels of pro-tumorigenic cytokines such as vascular endothelial growth factor (VEGF), interleukin 6 (IL-6), and a decrease of interferon-γ (IFN-γ);13 MDSC were increased after thoracotomy and promoted angiogenesis and tumor growth." (PMID 41208108, 2025). "In lung cancer, KRAS-mutant tumors were found to upregulate Tregs through IL-6 signaling." (PMID 40524071, 2025).
lung carcinoma (continued). "In a two-center study of lung cancer surgery patients, investigators found that CRP (and IL-6) levels rose in all patients postoperatively, including those who never developed any infection, meaning the markers’ additional predictive value was limited in the very early period." (PMID 41153812, 2025). "Also, we observed that IL-6 and TGF-β1 are both prognostic and predictive for the development of RILI in patients with lung cancer." (PMID 40746594, 2025). "Compared to NTA-MSCs, TA-MSCs from gastric cancer, lung cancer, pancreatic cancer and hepatocellular carcinoma (HCC) exhibit a notable elevation in cytokines like IL-6, IL-8 and TGF-β, along with genes including MMP1, S100A4, GREM1, and LOXL2, all of which are associated with tumorigenesis." (PMID 40676710, 2025). "Similar findings were observed with patients with lung cancer (n = 13) supplemented with 510 mg of EPA+ 340 mg DHA for 9 wk, which resulted in lower plasma concentrations of IL-6 and CRP (P < 0.05 for both) after 9 wk of treatment, compared with the placebo group (850 mg olive oil)." (PMID 40523478, 2025). "For this study, we collected and analyzed the correlation between clinical data and levels of serum inflammatory cytokines (interleukin [IL]-2, IL-6, IL-8, and tumor necrosis factor [TNF]-α) to guide the prognosis of patients who suffered advanced-stage lung cancer." (PMID 40265008, 2025). "The data indicate that IL-6 not only promotes its own expression but also activates the STING pathway (as evidenced by increased STING expression) and enhances autophagic flux (reflected by higher P62 and LC3-2B levels) in these lung cancer cell lines." (PMID 41378291, 2025). "By stimulating the JAK2/STAT3-C/EBPβ-IL6 pathway, IL-6 can promote the release of additional IL-6, creating a positive feedback loop in TAMs; thus, it promotes EMT, invasion, and migration of lung cancer in vivo and in vitro." (PMID 38424624, 2024). "The inflammatory microenvironment also promotes the progression and metastasis of lung cancer, and TNF-α CRP and IL-6 are common inflammatory factors, and their serum levels are generally elevated in lung cancer patients and are significantly correlated with tumor activity." (PMID 38957318, 2024). "Our clinical samples also confirmed higher IL-6 expression in lung cancer patients with bone metastasis compared to those without bone metastasis." (PMID 38993553, 2024). "IL-6 secreted by TAMs promotes lung cancer progression and metastasis in vivo and in vitro by activating the EMT pathway, which can be attenuated by the use of JAK2/STAT3 pathway inhibitors or IL-6 monoclonal antibodies." (PMID 38424624, 2024). "Given that lung cancer cells also secrete IL-6 and TNF-α, it is speculated that lung cancer cells and BMAs, by regulating OB function and inhibiting osteogenic differentiation, indirectly disrupt bone remodeling and promote lung cancer bone metastasis." (PMID 38571500, 2024). "The levels of inflammatory factors such as IL-1β, IL-6, TNF-α, and CRP in the serum of the lung cancer mice increased, promoting the activation of inflammatory cells and stimulating the release of inflammatory mediators, leading to an increased risk of systemic inflammatory response." (PMID 39594117, 2024). "Moreover, IL-1, IL-6, IL-8, TNF-α, and TGF-β secreted by lung cancer cells can activate downstream signaling pathways to increase VEGF expression, thereby promoting angiogenesis in the bone tumor microenvironment and indirectly facilitating bone metastasis." (PMID 38571500, 2024). "Animal studies demonstrated that aerobic exercise could reduce lung cancer inflammation, increase the levels of the anti-inflammatory cytokine IL-10, and decrease the levels of pro-inflammatory cytokines (such as TNF-α, IL-6, and IL-1)." (PMID 37691942, 2023).